MSTN (myostatin)
Diseases named in the same sentence as MSTN in open-access papers (continued):
Sharing a sentence is not in itself a finding about the gene and the disease.
sarcopenia (continued). "While the proportion of subjects with sarcopenia decreased with higher myostatin quartile, those with chronic kidney disease (CKD) defined as eGFR < 60 mL/min/1.73 m2 increased." (PMID 34299795, 2021). "In parallel, myostatin promotes the state of obesity, sarcopenia, and sarcopenic obesity, which promotes the release of inflammatory adipokines and hepatokines while inhibiting the release of myokines and other anti-inflammatory and antioxidant organokines." (PMID 33807959, 2021). "Clinically relevant and topical factors related to muscle wasting including sarcopenia, such as vitamin D, myostatin, insulin (related to diabetes), insulin-like growth factor I, mitochondria, and physical inactivity, are discussed." (PMID 34063269, 2021). "The drug‐induced increase of muscle mass did not drive improvement of physical function in the clinical trials of many potential sarcopenia drugs, such as MSTN inhibitors." (PMID 34553120, 2021). "Increased remodeling of muscle connective tissue and availability of myostatin have been also considered as possible initiators of sarcopenia." (PMID 33401549, 2021). "Background/Aims: Elevated levels of serum myostatin have been proposed as a biomarker for sarcopenia." (PMID 34299795, 2021). "The discovery of myostatin and its function has initiated a new phase of research into the treatment of sarcopenia." (PMID 34680417, 2021). "The potential of MSTN inhibition is efficient to work as an anti-sarcopenia and anti-cachexia agent." (PMID 34500839, 2021). "Hence, agents that either directly or indirectly disrupt myostatin signaling are being investigated by various pharmaceutical industries as a generic broad-spectrum therapeutic strategy to alleviate muscle loss arising from cachexia, sarcopenia, or muscular dystrophy." (PMID 32194441, 2020). "However, considering that preclinical/clinical data have reported that myostatin and sarcopenia are associated with hepatic fibrosis, patients with high serum myostatin levels could have an increased risk of developing HCC because of progressing hepatic fibrosis." (PMID 33198216, 2020). "Myostatin, which is growth differentiation factor 8, is considered to be another contributor to sarcopenia-related obesity in the transforming growth factor-β superfamily." (PMID 32344580, 2020). "The road to using myostatin as a biomarker in the diagnosis of sarcopenia and muscle wasting seems long, but it is worth taking." (PMID 32796600, 2020). "While, in a number of myopathies, myostatin is downregulated in order to counteract muscle wasting and, thus, seems to be a feasible biomarker of these disorders, in sarcopenia, the issue seems more complex." (PMID 32796600, 2020). "Pharmacological therapies for sarcopenia (testosterone, androgen receptor modulators, ghrelin agonists, myostatin inhibitors, ACE inhibitors) have been evaluated, but they are generally less effective than postulated (idem)." (PMID 33327483, 2020). "While the pathophysiology of spinal sarcopenia is complex, several studies have discussed the mechanism which leads to skeletal muscle atrophy, including insulin resistance, myostatin activation, mitochondrial function, and glucocorticoid response." (PMID 32344580, 2020). "In this direction, the evaluation of sarcopenia represents the most promising tool, whereas laboratory biomarkers (such as p16INK4a, myostatin and Insulin-like Growth Factor 1) are still at a very experimental stage." (PMID 33114320, 2020). "Preliminary studies are also investigating the role of expression levels of the marker of cellular senescence p16INK4a, as well as biomarkers of sarcopenia such as myostatin and insulin-like growth factor levels." (PMID 33114320, 2020). "Myostatin is a known regulator of muscle mass and has been examined as a therapeutic target to ameliorate symptoms of dystrophy, cachexia, and sarcopenia." (PMID 32194441, 2020).
sarcopenia (continued). "Due to a high abundance in skeletal muscle and its function as a myokine, myostatin is posing as a potential biomarker of muscle wasting and therapeutic opportunity for sarcopenia and cachexia." (PMID 32796600, 2020). "Myostatin increases in sarcopenia, by driving ubiquitin-proteasome-mediated protein degradation, while a myostatin deficiency has been shown to have beneficial effects on muscle size and mass, as well as adiposity and insulin sensitivity." (PMID 32878316, 2020). "Overall, myostatin is thought to be an important factor in the pathophysiology of sarcopenia and PAD." (PMID 32648665, 2020). "Studies have shown that elderly mice treated with myostatin inhibitors for 4 weeks exhibited improvements in sarcopenia and increased skeletal muscle insulin sensitivity." (PMID 32082422, 2020). "To date, five studies have investigated the association of SNPs with sarcopenia; limited to VDR, IL6, ACTN3 and MSTN polymorphisms." (PMID 32076017, 2020). "Hyperammonemia has been reported to transcriptionally upregulate myostatin through nuclear transport of p65 nuclear factor-ƙB, resulting in sarcopenia and poor prognosis." (PMID 32231160, 2020). "MSTN reduction has been proposed as a potential therapeutic approach to counter several muscle wasting diseases, including sarcopenia, and recent investigations support this assertion." (PMID 31751423, 2019). "Obesity increases insulin resistance, which suppresses muscle glucose uptake and protein anabolism, increases myostatin expression, and eventually progresses to sarcopenia." (PMID 30754663, 2019). "Second, we demonstrate that sarcopenia was attenuated through the antagonism of myostatin/activin signalling despite persistent defective DNA repair." (PMID 30916493, 2019). "One of the main mechanisms involved with this form of sarcopenia is myostatin (growth/differentiation factor 8), which inhibits skeletal muscle cell growth." (PMID 30258366, 2018). "To circumstantiate the influence of BMPs signaling in sarcopenia occurrence, we also investigated the expression of myostatin." (PMID 28202082, 2017). "Recent trials have focused on the prevention of cancer-related sarcopenia, including exercise training, nutritional supplements like omega-3 fatty acids or medication-based concepts such as myostatin inhibitors or melanocortin-4 receptor antagonists." (PMID 28050694, 2017). "Treatment with agents that can inhibit myostatin function (i.e., myostatin antagonists) in heart failure and sarcopenia models resulted in a reduction in Smad signaling, preventing loss of muscle mass." (PMID 28988574, 2017). "We set pre-sarcopenia as the dependent variable, and age, gender, BMI, and serum myostatin levels as the independent variables." (PMID 26785759, 2016). "In spite of the limitations above, the present study provided an insight supporting a potential role of MSTN in the pathophysiology of sarcopenia, frailty and PEW in the elderly with modest CKD." (PMID 26502079, 2015). "Many researchers have investigated the effect of inhibiting myostatin to counteract sarcopenia using animals." (PMID 25221510, 2014). "Several regulators (mammalian target of rapamycin, serum response factor, atrogin-1, myostatin, etc.)seem to modulate protein synthesis and degradation or transcription of muscle-specific genes during both sarcopenia and muscular dystrophy." (PMID 25221510, 2014). "On the other hand, myostatin is a potent inhibitor of muscle growth and is considered as a therapeutic target for muscle wasting including cachexia and sarcopenia, muscular dystrophy, and amyotrophic lateral sclerosis." (PMID 25221510, 2014). "Several positive and negative regulators (mTOR, SRF, atrogin-1, p62, and myostatin) have been proposed to enhance protein degradation or transcription of muscle-specific genes during both sarcopenia and muscular dystrophy." (PMID 25221510, 2014).
sarcopenia (continued). "More descriptive study seems to have detected such a limited but important adaptation of myostatin during sarcopenia." (PMID 25221510, 2014). "Myostatin inhibition seems to be an intriguing strategy for attenuating sarcopenia as well as muscular dystrophy." (PMID 22690213, 2012). "Myostatin inhibition seems to be the most interesting strategy for attenuating sarcopenia other than resistance training with amino acid supplementation." (PMID 22690213, 2012). "Several researchers have investigated the effect of inhibiting myostatin to counteract sarcopenia using animals." (PMID 22690213, 2012). "These lines of evidence clearly highlight the therapeutic potential of antibody-directed inhibition of myostatin for treating sarcopenia by inhibiting protein degradation and/or apoptosis." (PMID 22500226, 2012). "On the other hand, inhibiting myostatin to counteract sarcopenia has also been investigated only in animals." (PMID 22500226, 2012). "Myostatin inhibition is a promising therapeutic strategy to maintain muscle mass in a variety of disorders, including the muscular dystrophies, cachexia, and sarcopenia." (PMID 20161803, 2010). "Fst expression increases with age as a protective mechanism in response to the parallel elevation of myostatin, albeit this compensatory effect is ineffective in preventing sarcopenia." (PMID 19956636, 2009). "Prevalence of Sarcopenia according to serum ApoJ and MSTN levels." (PMID 40661742, 2025). "For sarcopenia, both Sharp score (OR = 1.008, 95% CI 1.002–1.014; P = 0.013) and elevated myostatin levels (OR = 1.222, 95% CI 1.015–1.472; P = 0.034) were significant risk predictors, whereas higher irisin levels conferred protection (OR = 0.963, 95% CI 0.936–0.990; P = 0.007)." (PMID 40593203, 2025). "Myostatin inhibitors, with their efficacy and low side effect potential, are promising as treatments for cancer cachexia, cirrhosis, skeletal muscle atrophy such as sarcopenia in the elderly, and neuromuscular diseases such as progressive muscular dystrophy." (PMID 39940810, 2025). "Many studies generally suggest that serum MSTN is highest in young individuals and decreases with age, which could pose challenges for using MSTN inhibitors to treat sarcopenia in older adults." (PMID 39340593, 2025). "This suggests that elevated myostatin levels may be a key factor in the development of age-related sarcopenia." (PMID 40926887, 2025). "Myostatin inhibitors are the most advanced therapies for the treatment of sarcopenia." (PMID 40806744, 2025). "The potential underlying mechanisms for the sex differences may include variations in muscle quality and in the regulation of muscle mass, such as differences in myostatin - a key factor in sex-specific patterns of sarcopenia and muscle wasting." (PMID 41210499, 2025). "Not-surprisingly, among transplant recipients, higher myostatin levels are associated with reduced muscle mass and sarcopenia." (PMID 41464844, 2025). "Furthermore, higher serum myostatin levels were associated with muscle atrophy during CKD and sarcopenia prevalence in older men, which can contribute to muscle wasting in this specific sex." (PMID 40648645, 2025). "We aimed to examine the association between serum ApoJ and MSTN levels and sarcopenia in older adults, with and without DM." (PMID 40661742, 2025). "Interestingly, myostatin levels have been reported to be a potential biomarker for sarcopenia, which seems to be specific for males." (PMID 40806703, 2025). "Two RCTs tested the benefits of myostatin inhibitor, bimagrumab, in patients with sarcopenia." (PMID 39764565, 2025). "Three studies evaluated the role of myostatin in sarcopenia following kidney transplantation." (PMID 41464844, 2025). "Conversely, higher MSTN levels were inversely associated with severe sarcopenia and low HS, independent of diabetes status." (PMID 40661742, 2025). "Consequently, targeting myostatin inhibition holds promise as a potential treatment for sarcopenia in CLD patients." (PMID 39796612, 2025).
sarcopenia (continued). "Conversely, heart disease may induce sarcopenia through inflammation, insulin-like growth factor-1, angiotensin, sex hormones, myostatin, physical inactivity, and malnutrition." (PMID 41440545, 2025). "Another open question is the role of biomarkers of biological aging and musculoskeletal reserve, including proteomic risk scores, low IGF-1, serum myostatin, TNF-α, and vitamin D, which may help identify individuals at risk for sarcopenia and poor recovery." (PMID 40700118, 2025). "Studies have shown that myostatin levels tend to be elevated in patients with sarcopenia." (PMID 41140691, 2025). "Furthermore, hyperammonemia itself can induce the expression of myostatin, a muscle growth inhibitor, thereby exacerbating sarcopenia and creating a vicious cycle." (PMID 41189897, 2025). "This insight could guide future investigations into ApoJ and MSTN as potential biomarkers and interventions for preventing sarcopenia in older adults." (PMID 40661742, 2025). "This study investigated the correlation of known sarcopenia biomarkers—adiponectin, myostatin, P3NP, CRP and TNF‐α—measured from plasma‐derived EVs with muscle mass, function and performance in an Osteoporosis Sarcopenia cohort at the Seoul National University Bundang Hospital." (PMID 40162588, 2025). "Thus, elevated serum myostatin levels contribute to the degradation of skeletal muscle, ultimately leading to sarcopenia." (PMID 40593203, 2025). "In patients with advanced alcoholic cirrhosis, hyperammonemia due to decreased ammonia clearance may lead to high levels of myostatin in muscle, resulting in the suppression of skeletal muscle protein synthesis and sarcopenia." (PMID 38256036, 2024). "Drug therapies such as testosterone and myostatin antibodies might potentially affect sarcopenia treatment." (PMID 38168920, 2024). "So, the reduction of MSTN could enhance protein synthesis, stop muscle degeneration, cease losing muscle mass during old age, and maybe reverse the sarcopenia process‌." (PMID 38409184, 2024). "The findings and the formula described in this study, based on a combination of age, albumin, myostatin, and adiponectin levels, could be a starting point for further research on the rapid initial assessment of sarcopenia in dialysis patients." (PMID 39125361, 2024). "Another study found that while the concentration of myostatin was lower in people with frailty or sarcopenia, the level of follistatin was higher in people with frailty, so a negative association was observed between myostatin and frailty, and sarcopenia." (PMID 39585121, 2024). "Protein and gene expressions of myostatin and follistatin were analyzed along the sarcopenia model." (PMID 39585121, 2024). "The determination of serum levels of MSTN and Act A may be useful in the early diagnosis of sarcopenia in IBD patients." (PMID 38542721, 2024). "Thus, inhibition of MSTN represents a strategy to stimulate muscle growth and prevent muscle wasting, as in sarcopenia." (PMID 39409095, 2024). "It is the colocalization of myostatin and stem cells in the muscles (myosatellite cells) of elderly individuals that is the consequence of the impaired ability of muscles to regenerate and of the sarcopenia development." (PMID 39590820, 2024). "Previous research results regarding myostatin concentration in sarcopenia have been inconclusive." (PMID 39125361, 2024). "In this cohort, serum levels of myostatin were significantly elevated in patients with sarcopenia." (PMID 39126043, 2024). "The gene expressions of myostatin and follistatin along the sarcopenia model, as in the analysis of protein expression, showed an opposite profile for both molecules: an inverted U-shape for myostatin (basal–up–down) and a U-shape for follistatin (basal–down–up)." (PMID 39585121, 2024). "The authors suggested that BMP and myostatin pathways are important for the induction of sarcopenia in OA and OP patients and could serve as therapeutic targets." (PMID 39683624, 2024).
sarcopenia (continued). "Even if the biological process underlying sarcopenia is not very clear, it is known that myostatin and follistatin are implicated in the balance between the synthesis and degradation of skeletal muscle." (PMID 39585121, 2024). "Hyperammonemia plays a critical role in the development of sarcopenia, regulates the rise of myostatin levels, and activates autophagia; elevated ammonia levels lead to the impairment of the mTOR pathway through increased mitochondrial dysfunction and ROS production." (PMID 39337069, 2024). "In dialysis patients, myostatin (AUC 0.79) and IL-6 (AUC 0.67) had a high discrimination value for sarcopenia, and we were able to develop a prediction model for sarcopenia, including age, albumin, adiponectin, and myostatin levels, with an AUC of 0.806 (95% CI: 0.721–0.891)." (PMID 39125361, 2024). "The regulation of muscle anabolism and catabolism by IGF1 and myostatin as well as inflammation have proven to be promising targets to protect from sarcopenia in general, and novel drug developments in these areas should be applied to pre-clinical models of CKD." (PMID 38791164, 2024). "Therefore, the influence of myostatin on sarcopenia was equivocal in the patients with CKD and ESRD." (PMID 36817773, 2023). "For instance, Myostatin and Irisin are directly involved in muscle metabolism and can be indicative of muscle atrophy, while BDNF and pro-inflammatory cytokines are linked to inflammation, a common underlying factor in both T2DM and sarcopenia." (PMID 37836433, 2023). "Therefore, although the physiological effect of myostatin inhibiting muscle growth is undisputed, clinical observations show disparate results in patients with sarcopenia related to liver disease." (PMID 36769301, 2023). "Myostatin is the most likely link between sarcopenia and BAT." (PMID 37153220, 2023). "One of the most interesting biomedical approaches to treat sarcopenia is myostatin therapy." (PMID 36768735, 2023). "Myostatin, which promotes bone resorption, is negatively correlated with muscle mass, and elevated myostatin levels may be related to lower BMD in sarcopenia." (PMID 36574105, 2023). "The authors concluded that myostatin may contribute to the higher prevalence of sarcopenia in women but acts as a homeostatic regulator of muscle mass in men." (PMID 36614282, 2023). "Furthermore, the suppression of muscle inflammation by luteolin has been demonstrated to lead to the inhibition of myostatin, indicating its protective effect against sarcopenia in obese individuals." (PMID 37832096, 2023). "As previously commented, many factors other than myostatin may contribute to sarcopenia in alcoholics." (PMID 36769301, 2023). "Future research may reveal promising pharmacological agents for treating sarcopenia, such as myostatin antagonists, selective androgen receptor modulators, and skeletal troponin activators." (PMID 37692743, 2023). "Additionally, in patients with sarcopenia, myostatin levels measured by PhA were significantly different from those in patients without sarcopenia." (PMID 37554924, 2023). "One explanation is that, since muscle cells are the main site of myostatin production, sarcopenia correlates with more advanced disease, which may lead to a decrease in myostatin production." (PMID 37554924, 2023). "MSTN is significantly elevated in the serum of patients with COPD, suggesting that MSTN may be associated with the development of COPD and sarcopenia." (PMID 37614743, 2023). "MSTN has been the subject of intense research since its discovery, and MSTN inhibitors are now being investigated as prospective therapeutics for muscle-wasting illnesses such as muscular dystrophy and sarcopenia." (PMID 35807547, 2022). "In conclusion, our data suggest that sarcopenia progression in ESLD may be linked to mitochondrial dysfunction, increased myostatin and potentially proteolysis." (PMID 35406665, 2022).